TBCC (tubulin folding cofactor C)
Description:
Tubulin-folding protein; involved in the final step of the tubulin folding pathway.
Synonyms: CFC
Tractability: PROTAC: ubiquitination databases record sites on it; its protein half-life has been measured.
Gene: Protein-coding gene on chromosome 6 (42,744,498 to 42,746,103, reverse strand). Ensembl gene ENSG00000124659.
Subcellular location: Cytoplasm
Subcellular location (Human Protein Atlas): Cytosol
Pathways (Reactome):
Metabolism of proteins: Post-chaperonin tubulin folding pathway
Gene Ontology:
Molecular function: GTPase activator activity; GTPase activity; protein binding; protein-folding chaperone binding; tubulin binding
Biological process: post-chaperonin tubulin folding pathway; protein folding; tubulin complex assembly
Cellular component: cytoplasm; cytosol; photoreceptor connecting cilium; cytoskeleton; microtubule
Genetic constraint (gnomAD): Loss-of-function variants: 5 observed, 5.04 expected, observed/expected ratio (o/e) 0.99, 90% interval 0.51 to 1.8. That is too few expected variants to judge how well the gene tolerates losing a copy. Missense variants: 102 observed, 87.21 expected, observed/expected ratio (o/e) 1.17, 90% interval 1 to 1.38. Synonymous variants: 40 observed, 35.36 expected, observed/expected ratio (o/e) 1.13, 90% interval 0.88 to 1.47.
Homologues: Orthologues: chimpanzee TBCC (99% identical), macaque TBCC (95% identical), pig TBCC (82% identical), dog TBCC (76% identical), mouse Tbcc (76% identical), rat Tbcc (71% identical), zebrafish tbcc (42% identical), Drosophila melanogaster Tbcc (29% identical), Caenorhabditis elegans tbcc-1 (21% identical).
Diseases named in the same sentence as TBCC in open-access papers:
TBCC is named in the same sentence as 2 diseases in open-access papers, as found by Europe PMC text mining. Sharing a sentence is not in itself a finding about the gene and the disease. The quoted sentences say what the papers report.
ovarian carcinoma (2 papers, 2020 to 2022). A malignant neoplasm originating from the surface ovarian epithelium. "miR-1251-5p was found to promote carcinogenesis and autophagy of ovarian cancer cell by targeting tumor suppressor TBCC." (PMID 32640974, 2020). "miR-1251-5p acts as an oncogene in ovarian cancer, suppressing TBCC and α/β-tubulin expression." (PMID 35310907, 2022).
breast carcinoma (1 paper, 2021). "Other genes, such as RTN4IP1 and TBCC, have been reported to be related to breast cancer progression." (PMID 33663517, 2021).